PITX1 (paired like homeodomain 1)
Description:
Sequence-specific transcription factor that binds gene promoters and activates their transcription. May play a role in the development of anterior structures, and in particular, the brain and facies and in specifying the identity or structure of hindlimb.
Synonyms: BFT; PTX1; POTX; CCF
Tractability: PROTAC: ubiquitination databases record sites on it.
Gene: Protein-coding gene on chromosome 5 (135,027,734 to 135,034,813, reverse strand). Ensembl gene ENSG00000069011.
Subcellular location: Nucleus
Subcellular location (Human Protein Atlas): Nucleoli
Gene Ontology:
Molecular function: protein binding; RNA polymerase II-specific DNA-binding transcription factor binding; sequence-specific double-stranded DNA binding; DNA-binding transcription factor activity; DNA-binding transcription factor activity, RNA polymerase II-specific; RNA polymerase II cis-regulatory region sequence-specific DNA binding; DNA binding; DNA-binding transcription activator activity, RNA polymerase II-specific
Biological process: anatomical structure morphogenesis; regulation of transcription by RNA polymerase II; skeletal system development; embryonic hindlimb morphogenesis; negative regulation of DNA-templated transcription; positive regulation of transcription by RNA polymerase II; regulation of DNA-templated transcription
Cellular component: nucleolus; nucleus; chromatin; cytoplasm; transcription regulator complex
Genetic constraint (gnomAD): Loss-of-function variants: 8 observed, 25.09 expected, observed/expected ratio (o/e) 0.32, 90% interval 0.19 to 0.57. The upper end of that interval is the gene's LOEUF score, 0.57, which puts it in group 2 of 6, group 1 being the genes least tolerant of losing a copy. Missense variants: 401 observed, 450.07 expected, observed/expected ratio (o/e) 0.89, 90% interval 0.82 to 0.97. Synonymous variants: 213 observed, 207.1 expected, observed/expected ratio (o/e) 1.03, 90% interval 0.92 to 1.15.
Homologues: Orthologues: chimpanzee PITX1 (100% identical), pig PITX1 (98% identical), macaque PITX1 (98% identical), guinea pig PITX1 (97% identical), mouse Pitx1 (97% identical), rat Pitx1 (96% identical), dog PITX1 (89% identical), tropical clawed frog pitx1 (79% identical), zebrafish pitx2 (62% identical). Paralogues in human: PITX2 (64% identical), PITX3 (53% identical), ARX (28% identical), DMBX1 (27% identical), OTP (25% identical), PAX7 (25% identical), ALX4 (25% identical), PAX3 (24% identical), RAX (24% identical), VSX2 (24% identical), OTX2 (23% identical), SHOX2 (23% identical), and 38 more.
Diseases named in the same sentence as PITX1 in open-access papers:
PITX1 is named in the same sentence as 98 diseases in open-access papers, as found by Europe PMC text mining. Sharing a sentence is not in itself a finding about the gene and the disease. The quoted sentences say what the papers report.
breast carcinoma (18 papers, 2011 to 2026). "For breast cancer, it was confirmed that the down-regulation of PITX1 improves prognosis, and this gene is associated with DNA methylation levels." (PMID 40724805, 2025). "PITX1 is often downregulated in cancer compared with normal tissues and is positively associated with patient survival in lung cancer, gastric cancer, breast cancer and esophageal cancer." (PMID 36334221, 2023). "In conclusion, PITX1 expression is upregulated in aggressive breast cancer subtypes associated with poor prognosis, including ER-negative, HER2-positive, lymph node-positive, and basal cell carcinoma." (PMID 37841446, 2023). "In breast cancer, PITX1 expression is enhanced, and high expression of PITX1 is associated with unfavorable clinical parameters and poor prognosis." (PMID 34868397, 2021). "Finally, PITX1 is under primary transcriptional control of ERα in breast cancer cells, and the protein it encodes is recruited to ERα-bound enhancers to modulate the transcriptional activity of the associated genes." (PMID 34215221, 2021). "However, the analysis of the association between PITX1 expression and the survival in breast cancer remains unclear." (PMID 32830857, 2020). "However, the analysis of PITX1 in breast cancer is rare and the association between PITX1 expression and breast cancer patients’ survival remains unknown." (PMID 32830857, 2020). "Functional assays were conducted to explore the role of PITX1 in promoting breast cancer proliferation and metastasis." (PMID 42065039, 2026). "Targeting the PITX1-PFKP axis with isoliquiritigenin offers a promising therapeutic strategy for breast cancer treatment." (PMID 42065039, 2026). "Recent studies provide further evidence implicating PITX1 as a tumor suppressor that correlates with patient survival and metastasis in various parenchymal tumors, including gastric carcinoma, breast cancer, esophageal carcinoma, lung cancer, and osteosarcoma." (PMID 40342824, 2025). "For example, PITX1 expression is decreased in breast cancer, lung cancer and Barrett’s adenocarcinoma relative to their normal tissues." (PMID 36334221, 2023). "Analogous to the observations in breast cancer, the interaction between PITX1 and ERα has been substantiated in ovarian cancer cell lines." (PMID 37841446, 2023). "The findings indicate that PITX1 has the potential to serve as a biomarker and therapeutic target for endocrine therapy in breast cancer treatment." (PMID 37841446, 2023). "We included ERα and FOXA1 (in lieu of FOXF1) based on their known relevance and protein-protein interactions in breast cancer, and PITX1 for relevance in other cancers and its novelty in ovarian cancer." (PMID 34215221, 2021). "PITX1 has been reported in a breast cancer repressive complex that contains RARA, FOXA1, and ERα; identified prior to MegaTrans." (PMID 34215221, 2021). "Four out of ten meet the threshold, which are the 11 datasets of overexpression of PITX1 gene level from a total number of 43 breast cancer datasets." (PMID 32830857, 2020). "Breast cancer patients with increased PITX1 gene showed worse relapse-free survival, disease-specific survival." (PMID 32830857, 2020). "The survival curve of different datasets based on the expression of PITX1 gene was used to analyze the prognostic value in breast cancer with PrognoScan." (PMID 32830857, 2020). "Breast cancer patients with PITX1 (blue) showed positive related with distant metastasis-free survival (P=0.024727, P=0.045388, P=0.022601, P=0.040643)." (PMID 32830857, 2020). "The present study demonstrated that the expression of PITX1 was up-regulated in breast cancer patients with respect to normal individuals according to Oncomine database." (PMID 32830857, 2020).
breast carcinoma (continued). "The expression of PITX1 gene compared with normal individuals and breast cancer patients was detected in 20 kinds of common cancers with tumor online database Oncomine." (PMID 32830857, 2020). "Bc-GenExMiner v4.3 software was used to evaluate the expression of PITX1 gene with several clinical parameters in breast cancer patients." (PMID 32830857, 2020). "In breast cancer patients, increased PITX1 expression is correlated with worse relapse-free survival, disease-specific survival and overall survival." (PMID 32830857, 2020). "“The estrogen-regulated transcription factor PITX1 coordinates gene-specific regulation by estrogen receptor-alpha in breast cancer cells...”." (PMID 23216862, 2012). "Silencing PITX1 significantly reduced breast cancer cell proliferation and suppressed glycolysis." (PMID 42065039, 2026). "However, there is contrary evidence that PITX1 expression is upregulated in breast cancer, prostate cancer, and lung cancer." (PMID 38540309, 2024). "The present study assessed the correlation between PITX1 expression and the prognostic factor of breast cancer by using various online analysis databases to explore the prognostic significance of PITX1 gene in the treatment of breast cancer." (PMID 32830857, 2020). "Up-regulation of PITX1 gene expression was found in breast cancer, colon cancer, kidney cancer, lung cancer and lymphoma, while down-regulation of PITX1 gene expression being detected in bladder cancer, cervical cancer, esophageal cancer and head and neck cancer." (PMID 32830857, 2020). "High PITX1 expression was correlated with poor clinicopathological features in breast cancer." (PMID 32830857, 2020). "High expression of PITX1 in our research may be because gene methylation level of breast cancer differs from other cancers." (PMID 32830857, 2020). "The expression of PITX1 gene was higher in HER2 positive breast cancer patients (P=0.0188)." (PMID 32830857, 2020). "As a transcription factor binding ERα in breast cancer, high PITX1 expression may have a certain impact on poor prognosis, which is worth further study." (PMID 32830857, 2020). "It indicates that breast cancer patients may benefit and have better survival with lower expression of PITX1 gene." (PMID 32830857, 2020). "Therefore, overexpression of PITX1 gene may be new biomarker factor related to the poor prognosis in breast cancer." (PMID 32830857, 2020). "According to an analysis of breast cancer public databases, COL10A1 and PITX1 have been considered as predictive biomarkers for the prognosis of BC." (PMID 34895070, 2021). "The expression of PITX1 gene was higher with advanced SBR grade and NPI of breast cancer patients (P<0.0001, P<0.0001)." (PMID 32830857, 2020). "We analyzed heat map of PITX1 and NOD2 gene expression in 50 gene QPCR analysis (pam50) to make sure positive co-expression relationship in breast cancer subtypes of TCGA database generated by UCSC Xena tool." (PMID 32830857, 2020). "Additionally, PITX1 expression was observed to be elevated in patients with ER-negative and HER2-positive breast cancer, as well as in those with lymph node invasion." (PMID 37841446, 2023).
breast carcinoma (continued). "The expression of PITX1 gene was significantly higher in SBR Grade, NPI, ER negative, HER2 positive, lymph node positive, triple-negative and basal-like status, which were related to poor prognosis of breast cancer respectively." (PMID 32830857, 2020). "The role of estrogen in the regulation of PITX1 expression has been illustrated in other diseases such as breast cancer, however, how estrogen regulates PITX1 expression in AIS has not been reported before." (PMID 29743058, 2018). "However, it is highly expressed in breast cancer, lung cancer, prostate cancer, and skin squamous cell carcinoma, indicating that the involvement of PITX1 in the process of carcinogenesis should not be underestimated." (PMID 37841446, 2023). "In addition, PITX1 was significantly higher in triple negative and basal breast cancer patients than in non-triple negative and non-basal breast cancer patients (P=0.013, P<0.0001)." (PMID 32830857, 2020).
melanoma (14 papers, 2008 to 2025). A malignant, usually aggressive tumor composed of atypical, neoplastic melanocytes. "In melanoma cell lines, the molecular mechanisms underlying how PITX1 suppresses carcinogenesis have been shown to involve inhibiting RAS activity and TERT expression." (PMID 36334221, 2023). "Loss of PITX-1 expression is seen in thin primary melanoma samples, with a 14-fold decrease in gene expression in thin primary compared to I.M. samples." (PMID 18442402, 2008). "The study revealed a marked reduction in PITX1 expression within melanomas, which was also correlated with melanoma staging." (PMID 37841446, 2023). "For example, in melanoma, unregulated PITX1 results in a reduction in cell proliferation and an increase in apoptosis." (PMID 36334221, 2023). "A study employed immunohistochemical and immunofluorescence methods to assess PITX1 expression in normal skin and melanoma tissue." (PMID 37841446, 2023). "Overexpressing miR-19b in melanoma cell lines (A2058) significantly suppressed PITX1 expression, resulting in a 1.5 to 1.7-fold increase in telomerase activity and enhanced melanoma cell proliferation." (PMID 37841446, 2023). "In melanoma, miR-19b is highly expressed, leading to decreased PITX1 expression compared to normal skin tissue." (PMID 37841446, 2023). "Recently, it was reported that interaction of PITX1 and ZCCHC10 contributes to TERT regulation in melanoma cells, and it was shown that PITX1 binds to the TERT promoter in gastric cancer cells." (PMID 35267575, 2022). "In malignant melanoma, PITX1 directly binds to the hTERT promoter, retrains hTERT transcription, and eventually triggers the inhibition of telomerase activity and proliferation." (PMID 34868397, 2021). "We have reported that PITX1 directly regulated SOX9 through targeting the promoter region in melanoma cells." (PMID 34526609, 2021). "In this study, we demonstrated the inhibitory effect of PITX1 in the proliferative phenotype of melanoma cell lines." (PMID 34526609, 2021). "Overexpression of PITX1 in melanoma cell lines resulted in a reduction in cell proliferation and an increase in apoptosis." (PMID 34526609, 2021). "Taken together, these findings suggest that PITX1 plays a suppressor role in the proliferative phenotype of melanoma cells as an upstream transcription factor of SOX9 and SOX10." (PMID 34526609, 2021). "Here we show that paired-like homeodomain transcription factor 1 (PITX1) plays a crucial role in the inhibition of melanoma progression through regulation of SRY-box transcription factors (SOX) gene family mRNA transcription." (PMID 34526609, 2021). "Overexpression of PITX1 induced apoptosis in 23% of the cells in vivo, but this is insufficient to explain the inhibitory effect on melanoma growth." (PMID 34526609, 2021). "Downregulation of PITX1 is observed in various cancers including malignant melanoma, oral, gastric, colon, lung, and bladder cancers." (PMID 31404068, 2019). "On the other hand, the suppression effects of hTERT transcription in transfectant cells that were overexpressed by introduction of PITX1 cDNA were weak when compared to those in microcell hybrid cells with human chromosome 5 in A2058 human melanoma cells." (PMID 31404068, 2019). "We next performed qRT-PCR analysis to determine the expression level of miR-19b in melanoma cell lines in which PITX1 protein expression is known to be lower than that of normal cells." (PMID 25643913, 2015). "Overexpression of PITX1 in B16-F10 cells and the human melanoma cell line A2058 induces downregulation of mtert and hTERT transcription, and knockdown of PITX1 with siRNA in B16-F10 MH5 and A2058 MH5 leads to increased mtert and hTERT expression." (PMID 26729168, 2015).
melanoma (continued). "To further examine the suppressive effects of miR-19b on PITX1 under more physiological conditions, we knocked down endogenous miR-19b expression in human melanoma A2058 cells using anti-miR-19b oligonucleotides." (PMID 25643913, 2015). "Similarly, in melanoma PITX1 can bind to RE1 (-592/-588) and RE3 (-520/-504) within the SOX9 promoter region, promoting SOX9 expression, apoptosis and inhibiting melanoma cell proliferation." (PMID 40342824, 2025). "For example, PITX1 has been shown to be down-regulated and to provide a positive prognosis in cancers such as osteosarcoma, oral squamous cell carcinoma, gastric cancer, malignant melanoma, esophageal, colorectal cancer, and lung cancer." (PMID 40342824, 2025). "Notably, PITX1 is frequently downregulated in malignant cancers, such as oral squamous cell carcinoma, malignant melanoma, esophageal cancer, lung cancer, colorectal cancer, and gastric cancer." (PMID 37841446, 2023). "In addition, PITX1 inhibited the development and progression of melanoma through targeting of the SOX signaling." (PMID 35465267, 2022). "Intriguingly, downregulation of SOX10 expression in tumor cells was associated with decreased SAMMSON expression, suggesting that PITX1 plays a crucial role as a regulatory factor to directly suppress melanoma growth thorough the SOX9-SOX10 and SAMMSON pathway." (PMID 34526609, 2021). "Thus, more detailed experiments using combinations of BRAF inhibitors and PITX1 inducing drugs for melanoma treatment will lead to the development of anticancer agents through novel targets." (PMID 34526609, 2021). "Moreover, PITX1 mRNA expression level was positively correlated with SOX9 mRNA expression level in human melanoma and normal skin tissues." (PMID 34526609, 2021). "Overexpression of PITX1 in SOX9low/SOX10high-expressing human melanoma cell lines (proliferative phenotype) inhibited cell proliferation and tumor growth in xenografts, but that of SOX9high/SOX10low-expressing human melanoma cell lines (invasive phenotype) did not." (PMID 34526609, 2021). "Taken together, the findings in this study indicate that PITX1 may act as a negative regulatory factor in the development and progression of melanoma via direct targeting of the SOX signaling." (PMID 34526609, 2021). "To determine whether PITX1 is important for melanoma growth in vivo, we performed subcutaneous tumor growth analysis using PITX1s-A2058 cells." (PMID 34526609, 2021). "Therefore, a detailed analysis of the role of PITX1 in the invasive phenotype of melanoma cells is an important issue to be addressed in the future." (PMID 34526609, 2021). "Interestingly, the introduction of an intact human chromosome 5 into melanoma A2058 cells more strongly suppressed hTERT transcription when compared with PITX1 cDNA-overexpressing clones." (PMID 31404068, 2019). "Co-expression of PITX1 and ZCCHC10 resulted in inhibition of hTERT transcription, in melanoma cell lines, whereas mutate-deletion of homeodomain in PITX1 that interact with ZCCHC10 did not induce similar phenotypes." (PMID 31404068, 2019). "To further determine the relationship between the expression level of miR-19b and that of PITX1 in vivo, we immunohistochemically analyzed PITX1 protein expression status in each of the fourteen clinical melanoma tissue specimens in which miR-19b expression levels had been assayed." (PMID 25643913, 2015). "Downregulation of PITX1 was reported in various types of human cancer including colon, prostate, bladder, lung, and gastric cancers, Barrett’s adenocarcinoma, oral tumors, and malignant melanoma." (PMID 26729168, 2015). "Additionally, co-transfection of an hTERT and mtert promoter construct with PITX1 in human and mouse melanoma cells inhibits the activities of both promoters." (PMID 26729168, 2015).